DACH1 (dachshund family transcription factor 1)
Diseases named in the same sentence as DACH1 in open-access papers (continued):
Sharing a sentence is not in itself a finding about the gene and the disease.
tumor (continued). "For example, inactivation of DACH1 or hyperactivation of SIX/EYA in breast epithelial cells leads to over-proliferation, tumor formation and invasion into blood vessels, resulting in distant metastases." (PMID 27203207, 2016). "Restoration of DACH1 expression in NSCLC cells significantly reduced cellular proliferation, clone formation, migration and invasion in vitro, as well as tumor growth in vivo." (PMID 25788272, 2015). "Here we showed that expression of DACH1 was significantly decreased in human NSCLC tissues and DACH1 abundance was inversely correlated with tumor stages and grades." (PMID 25788272, 2015). "To investigate the role of DACH1 in tumor biological behaviors, we generated HCC cell line that stably expressing DACH1." (PMID 25940701, 2015). "Among these rearrangements, 12 contained small exonal deletions, and most of the affected genes, including FHIT, CDH13, DACH1, and RBFOX1, have been reported as tumor suppressors or as deleted in cancer, suggesting their active role in tumorigenesis." (PMID 24937453, 2014). "DACH1 protein abundance was inversely correlated with the expression of PCNA and cyclin D1, tumor grade, and TNM stage." (PMID 25322986, 2014). "Overexpression of GATA3 in normal hMEC cells resulted in downregulation of BCL2, DACH1 and THSD4, supporting a tumor suppressor function for GATA3 under normal conditions." (PMID 25410484, 2014). "We show that some GATA3 effects shift from tumor suppressing to tumor promoting during tumorigenesis, with deregulation of three genes, BCL2, DACH1, THSD4, representing major GATA3-controlled processes in cancer progression." (PMID 25410484, 2014). "In humans, DACH1 is known to repress tumorigenesis in human breast and prostate cancers and down regulates EGFR and cyclin D1 in tumour cells." (PMID 24392136, 2014). "Similarly, overexpression of USP7 significantly promoted tumor proliferation in SW480 cells, while targeted knockdown of DACH1 negated this promotional effect." (PMID 40389405, 2025). "Specifically, miR‐31 directly targets the tumour suppressors CCAAT enhancer binding protein α (CEBPA) and dachshund family transcription factor 1 (DACH1), which decreases β‐catenin protein level via increasing Wnt/β‐catenin signalling inhibitors, such as AXIN1, CD9 and CD82." (PMID 38797942, 2024). "Therefore, miR‐31 possibly promotes PTC development through repressing tumour suppressors, especially CEBPA and DACH1." (PMID 38797942, 2024). "DACH1 deletion co-occurred with deletion of BRCA2, consistent with TCGA analysis demonstrating multiple pathways may be disrupted in a given tumor type." (PMID 37095257, 2023). "To assess the relationship between DACH1 homozygous deletions and outcomes, we queried copy number and overall survival data for three cBioPortal cohorts (TCGA PanCancer Atlas 2018, SU2C 2019, and MCTP) (n = 667 tumor samples)." (PMID 37095257, 2023). "DACH1 is generally considered as an inhibitor of cancer cell invasion and metastasis, while the molecule mechanism in the tumor cell migration is not entirely understood." (PMID 34772908, 2021). "At the molecular level, ATXN8OS sponged a tumor-suppressive miR-424-5p, thereby activating key oncogenes such as EYA1, DACH1, and CHRM3, which could be suppressed by Rg3 treatment." (PMID 33477683, 2021). "In concurrence with this notion, HLA peptide ligands from MUC2 and DACH1 were reliably detected from all the CRC tumor clones analyzed, whereas we did not detect the proteins in the quantitative proteomics screen." (PMID 33087703, 2020). "Moreover, ectopic expression of DACH1 significantly inhibited the expression of CXCL1, Ki67, and cyclin D1 in tumor tissues compared with A549 cells with empty vector." (PMID 31998654, 2019). "Based on the results of the ADC xenograft mice model, DACH1 efficiently inhibited the expression of CXCL8 and the pro-proliferative factors, such as cyclin D1 and Ki-67, which in turn significantly retarded the tumor growth." (PMID 29636079, 2018).
tumor (continued). "Of note, much attention has been focused on the ability of DACH1 to repress the process of Epithelial-Mesenchymal Transition (EMT) and to reduce the subpopulation of cancer stem cell (CSC), supporting its role as a novel tumor suppressor." (PMID 25940701, 2015). "In conclusion, this study confirms the frequent downregulation of DACH1 in two independent, large cohorts of HCC samples based on TMAs analyses, supporting its role as a tumor suppressor as well as an independent prognostic factor of overall survival in HCC patients." (PMID 25940701, 2015). "In BLBC, other GATA3-controlled cellular pathways, or lack of downstream ER signaling, may compensate for upregulation of BCL2, THSD4 and DACH1 by GATA3, resulting in a tumor suppressor function." (PMID 25410484, 2014). "DACH1 is methylated in 63.3% (62/98) of primary GC and 38% (19/50) of adjacent non-tumour tissues, while no methylation was found in normal gastric mucosa." (PMID 24912879, 2014). "DACH1 was found to be a predictor of specific survival but was not independent of hormonal therapy, clinical stage, tumour size or NPI status." (PMID 24392136, 2014). "Conversely, absent or weak DACH1 nuclear staining represents unopposed PELP1 mediated tumour cell growth." (PMID 24392136, 2014). "The tumor size was smaller in DACH1 expressed KYSE510 cells than in control (104.23±21.38 mm3 vs 494.65±81.98 mm3, P<0.01), and the tumor weight was less in DACH1 expressed KYSE510 cells than in control group (78±28 mg vs 182±37 mg, P<0.01)." (PMID 24743895, 2014). "Nuclear DACH1 expression appears to be a Luminal A biomarker predictive of good prognosis, but is not independent of clinical stage, tumour size, NPI status or systemic therapy." (PMID 24392136, 2014). "Moreover, this study discovered a previously unreported mechanism in which USP7 enhances the oncogenic activity of DACH1 by stabilizing it, a function not previously documented in tumor research." (PMID 40389405, 2025). "Additionally, metformin inhibits CXCL1 secretion in ESCC cells and tumor xenografts by enhancing AMPK phosphorylation and inducing the expression of the cell fate determinant Dachshund homolog 1 (DACH1), which subsequently leads to NF-κB inhibition and reduced MDSC migration." (PMID 40134607, 2025). "Additionally, the analysis revealed that high DACH1 mRNA expression did not significantly correlate with the overall survival rates of patients, suggesting that mRNA levels alone may not accurately reflect the association between DACH1 expression and tumor progression or prognosis." (PMID 40389405, 2025). "Therefore, DACH1 replaced the function of FOXM1 in the promoter of the target gene and competed with FOXC2 to inhibit the expression of genes involved in the invasion and metastasis of tumor cells." (PMID 36750914, 2023). "The imbalance of DACH1 and EYA2 may contribute to tumor initiation and development." (PMID 30761270, 2019). "Similarly, DACH1 (PR hypermethylated in tumor) was one of the IPA-defined nodes identified as a chromatin-binding protein that associates with other transcription factors to govern gene-expression during development." (PMID 26683690, 2015). "Whole-genome and transcriptome sequencing of tumor and adjacent normal tissue samples from NSCLC had identified novel alterations in genes involved in chromatin modification and DNA repair pathways, novel metabolic enzymes, as well as aberration of cell fate determination factor DACH1." (PMID 25477004, 2014). "Furthermore, while the experimental results revealed the functional significance of the interactions between DACH1 and USP7, the universality of these interactions in clinical samples and their role in tumor heterogeneity have not been thoroughly explored." (PMID 40389405, 2025). "Interestingly, another transcription repressor DACH1, known to mediate a negative FGF signaling feedback loop through FGF2 repression, showed ≥ 15-fold specific overexpression in the F2↑ tumor." (PMID 33853673, 2021).
cancer (56 papers, 2012 to 2025). A tumor composed of atypical neoplastic, often pleomorphic cells that invade other tissues. "The loss of DACH1 is frequently detected in various cancers and predicts the poor prognosis of cancer patients." (PMID 38093319, 2023). "DACH1 is a paralog of Drosophila dachshund (dac) gene in vertebra, which is expressed widely in normal adult tissues, and loss of DACH1 expression predicts poor outcome in many cancers." (PMID 33867818, 2021). "Pathways related to cellular injury and cancer predominated, suggesting DACH1 mutations lead to disease processes resulting in cellular injury and cancer." (PMID 33378353, 2020). "DACH1 was most associated with the cancer forming pathway followed closely by organismal injury and abnormalities, diseases of the endocrine system, and the gastrointestinal system." (PMID 33378353, 2020). "Inactivation of DACH1 in human cancer tissues was observed by mechanisms of gene deletion, mutation, or promoter hypermethylation." (PMID 25788272, 2015). "DACH1 staining intensity scores were also significantly lower in poorly differentiated (G3) cancers (p = 0.019 vs. G2 cancers), which were (as expected) significantly associated with MMR deficiency (P = 0.0019)." (PMID 24472434, 2014). "Thus, DACH1 governs cell fate through intracellular transcriptional regulation and also through heterotypic signaling that determines cancer-stromal interaction, a key hallmark of cancer." (PMID 26682253, 2015). "The loss of DACH1 in certain cancers might stem from cytosine hypermethylation at other possible regulatory regions of the DACH1 locus or from other types of epigenetic changes at this site." (PMID 24472434, 2014). "The mismatch repair defect was the result of epigenetic silencing of the MLH1 gene, and a similar phenomenon might have been responsible for the loss of DACH1 expression in some cancers." (PMID 24472434, 2014). "We therefore tested culturing organoids in 2D on collagen I-coated plates, which induced (i)REC marker genes, while repressing the stem cell markers LGR5 and DACH1, indicative of cancer cells transitioning into (i)REC states." (PMID 40393458, 2025). "This apparent contradiction highlights the possibility that DACH1 operates via diverse mechanisms in various cancer types." (PMID 40389405, 2025). "Dach1 is a transcription factor whose function has been extensively studied in other contexts and biological systems, notably in cancers and coronary angiogenesis." (PMID 40205161, 2025). "The GSEA results showed that several pathways were activated in the DACH1 low expression group, such as transcriptional misregulation in cancer, ECM-receptor interaction, and the NF-kappa B signaling pathway." (PMID 36959804, 2023). "DACH1 is broadly involved in cancer tumorigenesis, cell proliferation, and invasion via different pathways." (PMID 37766305, 2023). "Further research found that DACH1 expression was down-regulated in a variety of cancers and was closely related to poor prognosis." (PMID 36959804, 2023). "Enrichment analysis revealed that genes interacting with DACH1 were enriched for functions such as transcriptional misregulation in cancer, TGF-beta receptor signaling pathway, and negative regulation of signal transduction in absence of ligand." (PMID 36959804, 2023). "DACH1 is expressed in different cancer types, and it is correlated with poor prognosis and tumor progression of cancer patients." (PMID 34679437, 2021). "The four remaining transcription factors retrieved as potential MRs—DACH1, EPAS1, FOXA2, and FOXM1—have been extensively reported in associations with cancers in literature." (PMID 31503425, 2019). "Immunohistochemistry analysis showed that higher nuclear level of DACH1 was predictive of longer disease-free interval, cancer relapse-free survival and distant metastasis-free survival over 5 years post diagnosis." (PMID 28659634, 2017).
cancer (continued). "The vertebrate dac homologues, the DACH1 and 2 genes, are also important developmental regulators and cancer genes and a potential link between DACH genes and the Hh pathway in vertebrates awaits investigation." (PMID 27442438, 2016). "The next major challenge is exploring how to recover DACH1 gene expression to reverse the malignant activity of cancer cells in liver." (PMID 25940701, 2015). "Western blot showed that DACH1 was very weakly expressed in both cancer cell lines, in contrast DACH1 was abundantly expressed in HEK293 cells." (PMID 25322986, 2014). "DACH1 is increased in patients showing longer cancer specific survival and disease free interval and reduced metastasis formation (p<0.001)." (PMID 24392136, 2014). "The expression of DACH1 was reduced significantly in cancer tissue compared with the adjacent tissue (P < 0.01)." (PMID 24912879, 2014). "The repression of cyclin D1 transcription was a key target of DACH1 in regulating cancer cell proliferation." (PMID 25322986, 2014). "In contrast, among 12 cases of DACH1-expressed cancer tissue samples, only five cases were methylated (41.67%)." (PMID 24912879, 2014). "We used a well validated DACH1 polyclonal antibody to detect DACH1 expression in human renal tissue microarrays consisting of normal and different types of cancers by immunohistochemical staining." (PMID 25322986, 2014). "The role of DACH1 in cancer is multifaceted and varies depending on the specific cancer type." (PMID 40389405, 2025). "However, current studies on the synergistic effects of EYA1, SIX1, and DACH1 in promoting angiogenesis predominantly focus on cancer-related aspects, leaving the role of these genes in normal tissue differentiation incompletely understood." (PMID 41329538, 2025). "In addition, the second and third significant prognostic genes, DACH1 and GLIS1, have been widely reported that they are associated with the regulation of tumors and cancers." (PMID 35453785, 2022). "DACH1 has been identified in several human cancers as a novel tumor suppressor gene." (PMID 30261897, 2018). "Various studies have explored the potential of restoring DACH1 expression in cancer cells." (PMID 27203207, 2016). "Thus far, only a handful of reports have explored the value of DACH1 as a molecular marker for cancer prognosis." (PMID 25788272, 2015). "Moreover, gross observation indicated that cancer cells in vector group infiltrated into surrounding host tissues, while tumors in DACH1 group was not only smaller, but also clearly separated from surrounding host tissues." (PMID 25322986, 2014). "Among 20 cancer cases with lost/reduced DACH1 expression, 18 cases were methylated (90%)." (PMID 24912879, 2014). "Moreover, on average 60% of cells in low grade cancers (grade I) expressed DACH1, less than 20% cells in grade III tumors had detectable DACH1 expression." (PMID 25322986, 2014). "Restoration of DACH1 expression may be an innovative approach to cancer treatment." (PMID 36750914, 2023). "Therefore, DACH1 can be used as a potential molecule in cancer diagnosis and therapy." (PMID 36750914, 2023). "Although DACH1 has been studied in many cancers, its role in LSCC remains unknown." (PMID 30261897, 2018). "Furthermore, DACH1 may control stem cell gene expression preventing cancer cell migration needed for metastasis development." (PMID 24392136, 2014). "Because our MMR- cancers showed loss of gene expression due to epigenetic silencing of the MMR gene MLH1, we wondered whether their diminished DACH1 expression might be caused by methylation at the DACH1 promoter." (PMID 24472434, 2014). "However, DACH1 expression was absent in some carcinomas, most of which were DNA mismatch-repair deficient." (PMID 24472434, 2014). "The GSEA results showed that transcriptional misregulation in cancer, ECM-receptor interaction, and the NF-kappa B signaling pathway were activated in the DACH1 low expression group." (PMID 36959804, 2023).
cancer (continued). "It is well recognized that DACH1, SIX, and EYA, the key members of RDGN, have abnormal expression in various cancers." (PMID 36750914, 2023). "Mechanism exploration showed that DACH1 participated in the negative regulation of cell cycle, epithelial-mesenchymal transition (EMT) and reduction of the subpopulation of cancer stem cell (CSC)." (PMID 31998654, 2019). "The products of hub PCGs mainly function as protein binding molecule and were involved in important biological processes and signaling pathways in cancer (CDK1, MKI67, CENPF, COL4A6, DACH1, etc.)." (PMID 30026672, 2018). "Among the differentially expressed proteins, four factors (CNDP1, APOA4, DACH1 and BCL3) have previously been studied in different aspects of cancer, but only APOA4 and CNDP1 constitute secreted proteins." (PMID 25898255, 2015). "Meanwhile, epigenetically silenced expression of DACH1 in several kinds of cancers could be restored by HDACs inhibitors and resulted in reduced proliferation, thus providing a potential approach by the demethylase treatment to recover the expression of DACH1 in HCC patients." (PMID 25940701, 2015). "Functional studies have identified DACH1 as a negative regulator of TGF-β and Wnt signaling to repress cancer cell migration and invasion." (PMID 25788272, 2015). "The mRNA expression of DACH1 was inversely related to CXCL5 (R value = −0.77, p<0.025) and such inverse relationship was also observed in normal and cancer tissues." (PMID 25788272, 2015). "Comparison of the functions of DACH1 and USP7 with previous studies not only revealed their unique roles in CRC but also highlighted the potential of targeting their post-translational modifications for cancer therapy." (PMID 40389405, 2025). "Functionally, DACH1 significantly suppressed CXCL8-induced migration of A549 and SKLU cells, which indicated that the cancer-promoting effects of CXCL8 could be attenuated by the expression of DACH1 in ADC." (PMID 29636079, 2018). "In contrary to epigenetic changes and mRNA expression, previous studies failed to reveal the decreased protein abundance of DACH1 in cancer tissues." (PMID 25322986, 2014). "Further analysis using a human cancer stem cell qPCR array revealed that, relative to tnLCM or control, exposure of TNBC cells to tbLCM leads to downregulation of the transcription factor and putative tumor suppressor Dachshund homolog 1 (DACH1), a downstream regulator of FGF2." (PMID 38581619, 2024). "Fisher’s exact tests showed that DACH1 expression in MMR- cancers was significantly more likely to be partially/completely lost (staining extension: <70% of cells; p = 0.00016) or relatively weak (intensity scores of <5) (p = 0.054) than that observed in MMR+ cancers." (PMID 24472434, 2014). "DACH1 staining patterns did not appear to be related to TNM stages, although this finding needs to be confirmed in larger groups of MMR+ and MMR- cancers." (PMID 24472434, 2014).
kidney disease (6 papers, 2016 to 2024). "Further studies are needed to elucidate the precise mechanisms underlying these discrepancies and the role of Dach1 in podocytes, which will contribute to our knowledge of renal pathophysiology and potentially open avenues for therapeutic interventions in kidney diseases." (PMID 38805434, 2024). "Dachshund homolog 1 (DACH1), a cell-fate determination factor, was identified as a kidney disease risk gene." (PMID 37674991, 2022). "Our study, involving 60 patients, is the first systematic analysis of DACH1 expression from the perspective of renal disease." (PMID 27888806, 2016). "Dach1 is downregulated in injured podocytes in patients with various kidney diseases, which may further facilitate podocyte injury." (PMID 38805434, 2024).